CRP (C-reactive protein)
Diseases named in the same sentence as CRP in open-access papers (continued):
Sharing a sentence is not in itself a finding about the gene and the disease.
gout (continued). "In our study patients serum PCT level was significantly positively correlated with VAS (r = 0.39; p = 0.004), CRP (r = 0.52; p< 0.0001) and ESR (r = 0.28; p = 0.045) in gouty arthritis." (PMID 26182343, 2015). "A study has revealed that in gouty arthritis, crystal-induced inflammation is interleukin-1 production by activation of the inflammasome, blocking of IL-1 showed rapid decreases of VAS and CRP levels." (PMID 26182343, 2015). "We believe that an elevated UA concentration in patients with gouty arthritis may increase the WBC count, the concentrations of inflammatory markers, the ESR, and the CRP concentration." (PMID 39188875, 2024). "Of the 375 gout patients discontinuing pegloticase, median (IQR) laboratory changes following discontinuation were: SU: +2.4 mg/dL (0.0,6.3); eGFR: -1.9 mL/min (− 8.7,3.7); CRP: -0.8 mg/L (-12.8,0.0); and ESR: -4.0 mm/hr (-13.0,0.0)." (PMID 38609967, 2024). "We also found the serum IL-37 level to be closely associated with the serum uric acid level but not with ESR and CRP in gout." (PMID 39065733, 2024). "This study aimed to investigate the efficacy and safety of tart cherry supplementary citrate (TaCCi) mixture on urine pH, serum urate (sUA), C-reactive protein (CRP), and gout flares in gout patients initiating urate-lowering therapy (ULT), in comparison to citrate mixture and sodium bicarbonate." (PMID 37679816, 2023). "For example, serum urate demonstrated a Student’s t test p value of 0.11 (gout, mean 6.4 ± 1.9 mg/dL, CPP crystal arthritis, mean 5.3 ± 1.7 mg/dL), while CRP had a Mann-Whitney U test p value of 0.09 (median [IQR]; gout 10.9 mg/l [1.7–41]; CPPD 23.4 mg/l [10.7–119.6])." (PMID 34626261, 2022). "We assessed the association between the VPT levels and various clinical factors and our results suggested that the VPT level was positively correlated with age, duration of gout, SBP, C-reactive protein, ESR, and presence of tophi and negatively correlated with eGFR in all the subjects." (PMID 35280274, 2022). "As expected, gout and CPPD demonstrated markedly elevated ESR and CRP values." (PMID 34063875, 2021). "Among them, the expression level of TCONS_00004393 was positively correlated with ESR and CRP, and ENST00000566457 was positively correlated with ESR, CRP and Mo, indicating that they may be related to the inflammatory response of acute gout flare." (PMID 33600466, 2021). "Septic arthritis, gout, and pseudogout are known to have elevated serum inflammatory markers such as erythrocyte sedimentation rate (ESR) and C-reactive protein (CRP), rendering them of little use in differentiating the diagnosis of septic arthritis from systemic disease." (PMID 33423115, 2021). "In gout, it has been shown that sodium urate crystals are capable of inducing the formation of NET, and that these are protected from degradation by the fixation of C-reactive protein (CRP) molecules and of the complement." (PMID 32933031, 2020). "In addition, the levels of PMN-MDSCs in patients with gout were positively correlated with CRP levels, suggesting that PMN-MDSCs are related to acute inflammation in gout." (PMID 33154749, 2020). "Interestingly CRP, a marker of systemic inflammatory state and considered a marker for joint “activity” as well as marker for metabolic and cardiovascular risk, tended to lower levels during follow-up in patients with gout associated with MetS, but not in patients without it." (PMID 26131838, 2015). "In the baseline evaluation, patients with gout and MetS had significantly greater levels of CRP and greater but not significantly levels of Lep." (PMID 26131838, 2015).
gout (continued). "The levels of ox-LDL, hypersensitive C-reactive protein (hs-CRP), interleukin-1β, interleukin-6 (IL-6) and tumor necrosis factor-α (TNF-α) were measured in the plasma of 41 gout patients [28 in acute phase episode, 13 in intermittent phase (IP)], and in 40 healthy controls." (PMID 24068523, 2014). "In addition, abnormalities in laboratory indicators such as sUA, ESR, CRP, and WBC are of value in the diagnosis of lumbar gout, and changes in BUN and SCr levels may occur with late involvement of the kidneys." (PMID 36397389, 2022). "The measures of measures of disease activity (C-reactive protein, joint counts, patient global asessments) were measured on a monthly basis, and it is possible that these measures did not capture all gout flares, particularly if they occurred between a study visit." (PMID 31334482, 2019). "In addition to the fact that high CRP levels indicate infection- or non-infection-based inflammation, serum CRP levels positively correlate with serum urate levels and can be used as a gout determinant." (PMID 31739430, 2019). "According to our results, the clearing heat and removing dampness method of Chinese traditional medicine adjuvant treatment of Chinese medicine such as acupuncture and cupping could effectively reduce uric acid, C-reactive protein, and ESR in patients with gout." (PMID 30538765, 2018). "Herein, the proportion of PMN-MDSCs in PBMCs was higher in patients with gout than in HCs, and the expansion of PMN-MDSCs, not M-MDSCs, was positively correlated with levels of uric acid and CRP." (PMID 33154749, 2020). "However, acute-phase reactants including erythrocyte sedimentation rate (ESR, mm/h) and C-reactive protein (CRP, mg/L) in gout patients were not related to serum IL-37 levels (p > 0.05 of both)." (PMID 39065733, 2024). "However, ESR, CRP, and WBC are inflammatory indicators which are not very specific in the diagnosis of gout and can only be used as a reference." (PMID 36397389, 2022). "Data on C-reactive protein and erythrocyte sedimentation rates in the follow-up period were only reported in one study and demonstrated a nonsignificant reduction in CRP and ESR at days 10 and 30 in those initiated on allopurinol during an acute attack of gout." (PMID 27761603, 2016).
prediabetes (117 papers, 2010 to 2026). "Sensitivity analyses were performed on a sample excluding patients with prediabetes to assess the impact of prediabetes; the association between age at menarche and CRP remained significant with adjustment for model 4 (P for linear trend = .002)." (PMID 38912813, 2025). "It is also possible that elevated CRP levels have an underlying impact on the association between short sleep duration and prediabetes." (PMID 38566084, 2024). "The prediabetes stage is associated with an increased level of inflammatory markers, namely, CRP, IL-6, and TNF-α." (PMID 38068801, 2023). "The greatest risk of elevated CRP was detected in adults with prediabetes who were abdominally obese and consumed a high amount of sugar from SSBs." (PMID 36613000, 2022). "Our findings highlight that a positive association between sugar intake from SSBs and CRP levels was only observed in US adults with prediabetes." (PMID 36613000, 2022). "The main findings of this study indicated that high consumption of sugar from SSBs was positively associated with elevated CRP levels among individuals with prediabetes." (PMID 36613000, 2022). "Among the abdominally obese population, an increased risk of elevated CRP was estimated in US adults with prediabetes who were consumers of a medium or high amount of sugar from SSBs, when compared to non-SSB consumers with normal HbA1C." (PMID 36613000, 2022). "Prediabetes stage is associated with the increase in the level of inflammatory markers, that is, CRP, IL-6 and TNF-α." (PMID 33211181, 2021). "A 1 SD increase in the z-score of LH/FSH was only associated with prediabetes (p < 0.05; except in the model adjusted for CRP), but this association was weaker in comparison to the models based on FSH." (PMID 31467615, 2019). "Genetic polymorphisms of C-reactive protein (CRP) and their association with prediabetes and T2DM have been widely studied." (PMID 27478850, 2016). "Moreover, increased serum CRP levels have been linked to prediabetes, specifically decreased glucose tolerance." (PMID 38004306, 2023). "In participants with prediabetes, our results demonstrated an inverse association between fish oil supplementation and serum CRP levels, accounting for 5.9% of its relationship with CHD risk, aligning with the results of a previous meta-analysis of subjects with chronic diseases." (PMID 37513593, 2023). "Moreover, high CRP levels were found to be associated with a 2.2- and 8.1-times higher risk of developing prediabetes and T2DM, respectively, even after removing potential confounders, such as age, gender, and BMI." (PMID 38004306, 2023). "However, no study explored the association between SSB intake and the risk of elevated CRP in prediabetes." (PMID 36613000, 2022). "Compared to patients with prediabetes, those with T2D were more frequently of ethnic minority background, had more somatic comorbidities, lower coronary risk factor control, and higher levels of CRP." (PMID 30075751, 2018). "Chronic hyperglycaemia associated with prediabetes and T2DM stimulates the release of inflammatory cytokines such as CRP and IL-6." (PMID 41296388, 2025). "Previous research has suggested that individuals with prediabetes exhibit higher levels of C-reactive protein compared to those with normal glucose tolerance, indicating a heightened inflammatory response." (PMID 40566016, 2025). "The current meta-analysis revealed a significant effect of probiotics and synbiotics on reducing the level of the CRP marker in patients with prediabetes and T2DM (WMD: −0.46; 95% CI: −0.76, −0.15)." (PMID 41022286, 2025). "Results showed that normoglycaemic SAs had less non-esterified fatty acid (NEFA) suppression during the test, resembling prediabetes/T2D responses, and higher levels of plasma fetuin-A, CRP, and IL-6 but lower adiponectin, indicating AT inflammation." (PMID 38786765, 2024).
prediabetes (continued). "CRP and IL-10 were also discriminatory between prediabetes and T2DM, indicating their potential efficiency as biomarkers alongside BGL for the transition from prediabetes to T2DM disease status." (PMID 37383391, 2023). "Current research has identified multiple proteins in serum that are related to the occurrence and development of prediabetes, including C-reactive protein, lipopolysaccharide-binding protein, among others." (PMID 37964953, 2023). "Adults who had prediabetes possessed a higher prevalence of elevated CRP than adults with normal HbA1c (p < 0.001)." (PMID 36613000, 2022). "It was proven that accumulation of AGEs in psoriatic skin (evaluated as skin autofluorescence) is significantly higher in patients with intensified inflammation (measured as higher levels of C-reactive protein) and prediabetes (HbA1c 5.7–6.4%)." (PMID 36551298, 2022). "Other metabolic risk abnormalities included in the new MAFLD diagnosis were also considered in the present study, including plasma triglycerides, HDL, prediabetes, fasting glucose, HbA1c, and CRP." (PMID 36557250, 2022). "For example, a cross-sectional study showed higher CRP levels in a group of patients with prediabetes compared to those with standard glucose tolerance." (PMID 35494895, 2022). "In this study, 30.6% of US adults with prediabetes was observed to have elevated CRP when adjusted for demographic factors, substance use, physical activity, and personal medical conditions." (PMID 36613000, 2022). "Compared to the participants with a high fasting C-peptide level, those with a low C-peptide level had a higher proportion of women, a younger age, lower levels of mean hs-CRP and hs-cTnT, and a lower proportion of prediabetes or ND-T2DM (all P < 0.0001)." (PMID 36192784, 2022). "Lean MAFLD refers to FLD with normal BMI and metabolic disorders, involving WC, BP, TG, HDL-C, prediabetes, IR scores, and high-sensitivity CRP level." (PMID 36531447, 2022). "In this relatively healthy prediabetes cohort, the mean baseline measures for fasting glucose, insulin, lipoproteins, TG, hs-CRP, and blood pressure were generally within the normal range." (PMID 34201139, 2021). "The emergence of CRP among the top feature variables underlines the role of subclinical inflammation in the pathogenesis of IGT and prediabetes." (PMID 29615972, 2018). "In our study, levels of hepcidin were lower in persons with prediabetes compared to controls, when matched for BMI, WtHR, creatinine and CRP values." (PMID 28841871, 2017). "Oral magnesium supplementation decreased CRP levels in subjects with prediabetes and hypomagnesemia." (PMID 27547762, 2016). "Our data showed increased levels of CRP, IL-4, IL-10, and tryptase in prediabetes subjects and increased levels of CRP, IL-4, and IL-10 in T2DM subjects compared with normal glucose subjects." (PMID 27478850, 2016). "We extend the literature by showing that early on in this spectrum otherwise healthy disease free obese cardio metabolically neutral subjects with very high levels of hs CRP not only have prediabetes, but also have prehypertension." (PMID 20659335, 2010). "The subjects who had prediabetes, also exhibited prehypertension: mean BP 127/80 mm Hg, along with a significantly higher hs CRP (16.9 ± 9 mg/L; p < 0.0001) and fibrinogen (599 ± 95 mg/dL; p < 0.0002)." (PMID 20659335, 2010). "The increased levels of CRP in prediabetes suggest that even minor early metabolic disturbances may enhance vascular risk, hence the stratification and need for early intervention in such cases." (PMID 41296388, 2025). "Indeed, we have shown higher levels of IL-6 and fibrinogen in NT2D and T2D compared to prediabetes, as well as higher levels of CRP in prediabetes, NT2D and T2D compared to healthy controls." (PMID 37814622, 2023). "Increasing the concentration of CRP in prediabetes may reduce insulin sensitivity and eventually worsen glycemic status by raising blood sugar." (PMID 35659064, 2022).
prediabetes (continued). "Increased levels of inflammatory markers, such as C-reactive protein (CRP), may be linked to the mechanism of how the loss of sleep may lead to prediabetes." (PMID 35494895, 2022). "Increased CRP concentrations have been reported in people with prediabetes." (PMID 35659064, 2022). "Elevated C-reactive protein may be a potential mechanism linking prediabetes and poor sleep quality that warrants further investigation." (PMID 36014897, 2022). "In addition, serum sVAP-1 levels also negatively correlated with CRP levels in prediabetes patients." (PMID 31146362, 2019). "The levels of CRP were positively correlated with fasting and 2-h post-load glucose concentrations in individuals with impaired glucose tolerance, and individuals with prediabetes also had higher CRP levels." (PMID 30454030, 2018). "In future research, multivariate adjustments could be applied by including lifestyle factors as covariates in regression models (e.g., adjusting CRP levels for smoking status or BMI), which would help distinguish the independent contribution of prediabetes from these confounders." (PMID 41296388, 2025). "Physical activity promotion with dietary and lifestyle modification may reduce the level of leptin and interleukin-6, but we are uncertain if there is any effect on levels of adiponectin, C-reactive protein, and tumour necrosis factor-α in the individuals with prediabetes." (PMID 38068801, 2023). "This review suggests that physical activity promotion with dietary and lifestyle modification may reduce the level of leptin and interleukin-6 but are uncertain if there is any effect on levels of adiponectin, C-reactive protein and tumour necrosis factor-α in the individuals with prediabetes." (PMID 33211181, 2021). "This systematic review and meta-analysis demonstrate that probiotic and synbiotic supplementation effectively reduces inflammatory markers, including CRP, IL-6, and TNF-α, in adults with prediabetes and T2DM." (PMID 41022286, 2025). "The participants with prediabetes had higher TC, TG, LDL, and CRP than the normal participants (p < 0.001)." (PMID 27213415, 2016). "Our data showed increased levels of hypersensitivity C-reactive protein (hs-CRP), interleukin (IL-4), IL-10, and tryptase in prediabetes subjects and hs-CRP, immunoglobulin E (IgE), IL-4, and IL-10 in T2DM subjects." (PMID 27478850, 2016). "The Health, Aging, and Body Composition study demonstrated that dysglycemia is associated with inflammation, as expressed by an increase in CRP, tumor necrosis factor-alpha (TNF-a), and interleukin-6 (IL-6) levels among older people (70–79 years) with prediabetes and DM." (PMID 39335474, 2024). "This review suggests that the physical activity promotion program may reduce the level of leptin and IL-6, but whether there is any effect on the level of adiponectin, CRP, and TNF-α in individuals with prediabetes is uncertain." (PMID 38068801, 2023). "For this purpose, we assessed the relationship between serum Vit D levels and acute phase reactants such as CRP, fibrinogen and ferritin and pro-inflammatory markers such as IL-1β, IL-6, IL-8, TNF-α, NF-κB and MAPK in newly diagnosed prediabetes and type 2 DM patients." (PMID 38136648, 2023). "Moreover, the modulating effects of probiotics or synbiotics on inflammation (CRP and TNF-α levels) were more pronounced in patients with T2DM compared to individuals with prediabetes." (PMID 36239789, 2023). "Nonetheless, previous studies suggested that pro-inflammatory diet could promote low-grade inflammation that is characterized by elevated pro-inflammatory markers, namely, CRP, TNF-α, and interleukin-6 which may lead to prediabetes and IR." (PMID 35250879, 2022). "The evaluation of the anti-inflammatory effects of metformin in people with prediabetes and T2DM have shown that treatment with this agent resulted in decreased plasma insulin level, plasminogen activator type 1 (PAI-1) antigen, C- reactive protein (CRP) and fibrinogen." (PMID 33562458, 2021).
prediabetes (continued). "This review suggests that physical activity promotion programme may reduce the level of leptin and IL-6, but it is uncertain whether there is any effect on the level of adiponectin, CRP and TNF-α in individuals with prediabetes." (PMID 33211181, 2021). "Interestingly, metformin or exercise training monotherapies lowered systolic blood pressure and C-reactive protein (CRP) by ~7–8 and 20–25%, respectively, in people with prediabetes." (PMID 32849302, 2020). "This study revealed that the IL1-β, IL-6, IL-8, TNF-α, NF-κB and MAPK levels as pro-inflammatory markers and CRP, fibrinogen and ferritin as serum acute phase reactants were significantly increased in the prediabetes and T2DM groups compared to nondiabetes group." (PMID 38136648, 2023). "In fact, individual mean CRP levels during observation period were significantly higher in subjects with incident prediabetes than subjects without prediabetes (median 0.06, 25th–75th percentile 0.04–0.11 vs median 0.05, 25th–75th percentile 0.04–0.09, p < 0.001)." (PMID 28430803, 2017). "The group with prediabetes (n = 11; W = 8, M = 3) with significantly higher FSG (106 ± 3 mg/dL; p < 0.0001), HbA1c (5.9 ± 0.5%; p < 0.002), had prehypertension (BP: 127/80 mm Hg) and significantly higher hs CRP (16.9 ± 9 mg/; p < 0.0001) and fibrinogen (599 ± 95 mg/dL; p < 0.0002)." (PMID 20659335, 2010). "Subgroup analysis for CRP and TNF-α levels revealed a significant effect was pronounced in those with a definite diagnosis of T2DM and not in the patients with prediabetes." (PMID 41022286, 2025). "This study investigated electronic health record data and also found that CRP levels (besides HDL cholesterol and alanine aminotransferase) predicted the progression from normoglycemia to prediabetes, though no information on statistical significance of the prediction improvement was reported." (PMID 30599058, 2019).